IL6 (interleukin 6)
Diseases named in the same sentence as IL6 in open-access papers (continued):
Sharing a sentence is not in itself a finding about the gene and the disease.
prostate carcinoma (continued). "One possible mode by which IL-6 may influence progression of prostate cancer to the hormone-refractory state is by activating the IL-6 receptor/JAK1/STAT3 pathway, resulting in differentiation and inhibition of apoptosis." (PMID 17595657, 2007). "Indeed, the increase in proliferation rate observed in prostate cancer cell line models in response to IL-6 has been demonstrate to be via activation of STAT3." (PMID 17595657, 2007). "In addition, in vitro studies have demonstrated that IL-6-dependent activation of the JAK/STAT3 pathway is accompanied by transition from hormone-sensitive to hormone-insensitive prostate cancer cell growth." (PMID 17595657, 2007). "Finally, recent evidence in a phase I clinical trial has suggested that the proteasome inhibitor bortezomib has activity against human prostate cancer and reduces the expression of serum IL-6 and PSA levels in some patients." (PMID 16278667, 2005). "Studies of IL-6 in prostate carcinoma provide support for the hypothesis that direct local production of IL-6 by malignant cells significantly contributes to elevated serum levels." (PMID 15150588, 2004). "As prostate cancer cells also express high levels of IL-6 receptor, IL-6 may elicit both paracrine and autocrine responses." (PMID 15150588, 2004). "Thus, during the progression of prostate cancer to the hormone refractory phenotype, IL-6 undergoes a functional transition from paracrine growth inhibitor to autocrine growth stimulator." (PMID 15150588, 2004). "The development of IL-6R superantagonists should allow the role of IL-6 in hormone-dependent and -independent conditions, such as breast and prostate cancer, to be elucidated and may lead to their use as novel therapeutic options for their treatment." (PMID 12592380, 2003). "Moreover, in prostate cancer, the secretion of IL-6 by CAFs indicates a predominance of iCAFs." (PMID 40453074, 2025). "Thus, CA might act as a therapeutical application against prostate cancer by targeting the IL-6/JAK/STAT3 signaling axis." (PMID 39574470, 2024). "In addition to its direct effect on tumours, IL‐6 may regulate the immune microenvironment of prostate cancer by enriching immune cells." (PMID 36524848, 2023). "Interestingly, treatment with IL‐6 was described to induce NED in LNCaP prostate cancer cells." (PMID 35653631, 2022). "Thus, direct IL-6 stimulation in certain immune cell populations could induce an anti-inflammatory signal in prostate cancer and hypertrophy." (PMID 35464825, 2022). "In addition, elevated IL-6 may contribute to the conversion of TGF-β1′s role as a prostate cancer promoter." (PMID 36140220, 2022). "Indeed, earlier work has shown IL-6 to directly promote the growth of prostate carcinoma cells." (PMID 36371231, 2022). "In addition, Propionibacterium acnes (P. acnes) stimulate prostate cells to secrete interleukin (IL)-6 and IL-8, which may be related to the occurrence and development of prostate cancer." (PMID 36003378, 2022). "Interestingly, IL6, as a member of the IL6 family and a pleiotropic cytokine, has been shown to accumulate in solid tumors of human colorectal cancer, breast cancer, gastric cancer, prostate cancer, and osteosarcoma." (PMID 34094941, 2021). "In PTEN-deficient prostate cancer, prostate-specific deletion of CHD1 resulted in markedly delayed tumor progression and prolonged survival, which was associated with a reduction in MDSCs and an increase in CD8+ T cells through IL-6, a key transcriptional target of CHD1." (PMID 35003065, 2021). "Action of IL-6 in prostate cancer may also be supported by other cytokines, such as oncostatin." (PMID 34204596, 2021). "Similarly, Heidarian and Keloushadi (2019) reported that this monoterpene acts through the negative regulation of pERK1/2, pSTAT3 and pAKT expression, suggesting that inhibition of interleukin-6 (IL-6) signaling pathways can be a promising target for prostate cancer treatment." (PMID 34305611, 2021).
prostate carcinoma (continued). "Our findings suggest that prostate epithelial cells produce IL-6 when inflamed by T. vaginalis infection, this polarizes macrophages to the M2 type, and crosstalk with these differentiated (M2) macrophages promotes the proliferation and migration of prostate cancer cells." (PMID 32196489, 2020). "The cytokine IL-6 has been suggested as one of the most promising immunological markers that might be useful as additional factor for prediction of radiation-induced normal tissue toxicity, not only for prostate cancer, but also for other types of cancer." (PMID 33149212, 2020). "Thus, we tested whether IL-6 secreted from preadipocytes and TAMs affects migration and invasion of prostate cancer cells." (PMID 32971847, 2020). "Finally, IL-6 is a pro-inflammatory cytokine with a well-established role in promoting androgen-independent phenotype of prostate cancer cells as well as immunosuppression in the prostate tumor microenvironment, which can be induced by a plethora of danger signals." (PMID 31013891, 2019). "In addition to its role as an immunomodulatory cytokine, IL-6 acts as an autocrine and paracrine growth factor and has been reported to be involved in prostate cancer cell growth by activating signaling pathways/signal transducers and activators of transcription factors, including the STAT family." (PMID 30646518, 2019). "The value of targeting the IL6 pathway in prostate cancer including CRPC remains unclear." (PMID 29540470, 2018). "Moreover, targeting IL-6 signaling could be a promising strategy for sensitizing prostate cancer to ADT + local RT in the clinic, particularly for metastatic CRPC." (PMID 30587810, 2018). "Thus, clearly the IL6-Jak2-STAT5 axis plays a regulatory role in prostate cancer and metastasis." (PMID 30558204, 2018). "Prostate cancer cell lines under the influence of the IR (innate or adaptive) presented a significant increase of IGF-1Ec upregulation (similar to the one observed after IL-6 treatment) (p < 0.001, students t test, n = 3) which was abolished when these cells were treated with anti-IL-6R antibody." (PMID 30134795, 2018). "Previous studies have shown that C. acnes has the capability to stimulate secretion of IL6 and CXCL8 by prostate epithelial cells in vitro, and a microenvironment containing high levels of these two inflammatory mediators has been associated with prostate cancer progression." (PMID 30473726, 2018). "In addition, IL-6/IL-6R is known to be the key signaling pathway in prostate cancer." (PMID 29868029, 2018). "Thus, at a systemic level, IL6 rewires host metabolism to raise circulating cholesterol levels that may further facilitate prostate cancer progression towards a CRPC phenotype." (PMID 29540470, 2018). "The inflammatory cytokine IL-6 has been shown to induce the nuclear translocation of androgen receptors in prostate cancer cells and to activate the androgen receptors in a ligand-independent manner, suggesting it may contribute to the development of a castrate-resistant phenotype." (PMID 27577074, 2017). "Although the significance of IL-6 in prostate cancer progression is well established, whether IL-6 plays a causative role in prostate cancer risk and early development is not clearly well defined." (PMID 28077171, 2017). "In summary, IL-6 rs1800795 polymorphism may not have an independent influence on the susceptibility to prostate cancer in general population, but it may significantly increase the risk in African-American males." (PMID 28296724, 2017). "To determine whether the link between ESE3/EHF and IL-6 observed in our cell line models was seen also in clinical samples, we analyzed gene expression data from two large (n = 545 and n = 131, respectively) human prostate cancer patients datasets." (PMID 27732936, 2016).
prostate carcinoma (continued). "Moreover, IL-6 was shown to be significantly over-expressed in pancreatic cancer tissue, and serum levels were significantly elevated in cachectic compared to non-cachectic patients with pancreatic cancer and prostate cancer." (PMID 26856534, 2016). "However, the IL-6 upstream trans-signaling pathway in prostate cancer remains poorly understood." (PMID 26252635, 2015). "In this study, we identified several genes including the cytokines Il-6, Tgfb2, Cxcl1, and Ctgf, metallopeptidases Mmp13, Adamts1, Adamts4, and Adamts5, and transcription factors Junb, Fos, Stat3 and Cebpb that were up-regulated in osteoblasts as a result of prostate cancer–osteoblast interactions." (PMID 27600237, 2015). "Therefore, AR may be the common target for IL-6 and miR-21 in prostate cancer, with miR-21 playing an intermediary role in activating IL-6 to regulate PDCD4 expression." (PMID 26252635, 2015). "To assess whether TLR9 contributes to prostate cancer progression, we selected three prostate cancer models: parental LNCaP cells, LNCaP-S17 cells stably expressing IL-6 and PC3-luc cells as representing less or more advanced stages in the progression to androgen-independence, respectively." (PMID 26046794, 2015). "An integrated network of Tgfb2, Il-6, Cxcl1, and Ctgf interactions revealed several putative binding partners in osteoblasts and/or prostate cancer and suggested that these secreted cytokines may control up-regulated transcription factors Junb, Cebpb and Stat3 in osteoblasts." (PMID 27600237, 2015). "Finally, the data from the placebo arm (1359 men) of the Prostate Cancer Prevention Trial (PCPT) demonstrated that circulating levels of inflammatory markers, including elevated CRP and interleukin-6 (IL-6), were associated with risk of incident, symptomatic BPH." (PMID 24688539, 2014). "IL-6 is a pleiotropic cytokine originally identified as a regulator of immune and inflammatory responses, and evidence has been accumulating that IL-6 may also play an important role in prostate cancer progression to an androgen-independent state." (PMID 24296978, 2014). "There are some transcriptional factors, such as AP-1, CCAAT enhancer binding protein, cAMP response element binding protein, as well as NF-κB reported to have potential binding sites within the human IL-6 gene promoter area and, thus, could interfere IL-6 gene expression in prostate cancer cells." (PMID 24664372, 2014). "Therefore, specific targeting IL-6TS in prostate cancer patients, might represent an interesting way to refine the currently available experimental anti-IL-6 therapies since sIL-6R and IL-6 are altered in patients with a worse prognosis." (PMID 23497644, 2013). "The predominant activation of trans-signaling IL6/soluble IL6R pathway in aggressive prostate cancer, together with the functional IL6R Asp358Ala influence in this mechanism, supports the increased risk for high-grade prostate cancer we observed for C carriers (Ala carriers)." (PMID 22792137, 2012). "Interleukin 6 (IL-6) is one such molecule that may implicate in prostate cancer progression." (PMID 21991434, 2011). "Autocrine IL-6-induced Mcl-1 could protect prostate cancer cells from apoptosis." (PMID 21880146, 2011). "Thus, thrombin induced IL-8 and VEGF release from prostate cancer cells and IL-6 production from synovial fibroblasts was blocked by siRNA of PAR-1, trypsin induced IL-8 production from human gastric epithelial cells (MKN45 cells) was inhibited by siRNA of PAR-2." (PMID 19732468, 2009). "Further, IL-6 activates androgen receptor-mediated gene expression in LNCaP cells in vitro, suggesting that IL-6 may play a critical role during the progression of prostate cancer." (PMID 19242540, 2009). "If induced by STAT3 and IL-6, CD46 expression protects cancer cells against complement lysis and fosters a pro-tumoral profile in breast and prostate cancers." (PMID 40370471, 2025).
prostate carcinoma (continued). "First, network pharmacology was used to predict the potential targets of Osthole, identifying 68 targets shared with prostate cancer, including AKT1, TNF, IL6, STAT3, and CTNNB1." (PMID 40978029, 2025). "In their pilot study with 15 prostate cancer patients, they evaluated the effects of a 24-week HOET on IL-1α, IL-5, IL-6, IL-12, TNF-α, and IFN-γ." (PMID 40498221, 2025). "A higher level of IL-6 was observed in the metastatic specimens of prostate patients, and plays an important role in EMT induction, leading to prostate cancer invasiveness." (PMID 39941895, 2025). "Chronic inflammation in the tumor microenvironment can lead to increased cytokine production (e.g., IL-6, TNF-α, IL-1β), which promotes both prostate cancer progression and the survival/proliferation of abnormal plasma cell clones in MGUS." (PMID 41374992, 2025). "We have identified targets such as AKT1, TNF, IL6, STAT3, and CTNNB1 in Osthole’s inhibition of prostate cancer, along with pathways including the TNF signaling pathway, the Interleukin-6-17 (IL-6-17) signaling pathway, and the prolactin signaling pathway." (PMID 40978029, 2025). "It has been reported that upregulation of NSD2 is correlated with increased expression of IL‐6 and TNF‐α via NF‐κB in prostate cancer." (PMID 38400589, 2025). "Interferon gamma (IFNγ), interferon alpha (IFNα), and interleukin 6 (IL6)-Janus kinase (JAK)-signal transducer and activator of transcription 3 (STAT3) signaling were assessed in enzalutamide-sensitive and -resistant prostate cancer cells." (PMID 41097714, 2025). "In another study in prostate cancer, PKD3 knockdown was responsible for the reduced secretion of pro-inflammatory cytokines IL-6, IL-8, and GROα." (PMID 38323010, 2024). "This inflammatory response is a crucial factor in HFD-induced prostate cancer growth, with HFD potentially leading to increased IL-6 expression in prostate tissue and triggering prostate cancer." (PMID 38402385, 2024). "CA treatment on IL-6, JAK1, and p-STAT-3 (tyr705) expression in prostate cancer cells PC-3 were examined by western blotting." (PMID 39574470, 2024). "Keywords like microbiota, radiotherapy, gene expression, prostatectomy, IL-6, IL-1β, TNF-α, and STAT3 hold central positions within the prostate cancer domain, reflecting their frequent study." (PMID 39355131, 2024). "Given the relationship between obesity, proinflammatory factors (e.g., IL-6, TNFR2, and CRP), and prostate cancer progression, we also examined the effect of a KD on markers of inflammation." (PMID 39519548, 2024). "IL-6 mediated JAK/STAT3 expressions regulate the proliferation and antiapoptosis that leads to prostate cancer metastasis and migration." (PMID 39574470, 2024). "In this study, we investigated the role of CA in inhibiting the Interleukin-6 (IL-6)/Janus kinase (JAK)/Signal transducer and activator of transcription-3 (STAT-3) mediated suppression of the proliferation signaling in human prostate cancer cells." (PMID 39574470, 2024). "The overexpression of IL-6 and JAK-1 is required for the STAT-3 activations that lead to prostate cancer proliferation and migrations." (PMID 39574470, 2024). "The demonstrated impact on tumor cell viability, proliferation, migration, and IL-6 levels positions GNP9.24.58 as a promising candidate for targeted and effective prostate cancer therapy." (PMID 38396953, 2024). "We then proposed that prostate cancer patients tended to benefit from CIRT, as evidenced by decreased TGF-β and IL-6." (PMID 36138265, 2023). "However, the molecular mechanisms responsible for the EHF-mediated inhibition of the STAT3 pathway in TNBC cells might be different from those in prostate cancer cells because the mRNA level of IL-6 was significantly increased by EHF overexpression in MDA-MB-453 cells." (PMID 37958443, 2023).
prostate carcinoma (continued). "Among various causes of prostate cancer androgen receptor (AR) signaling, PTEN/PI3K/AKT/mTOR pathway, IL6/STAT3 and STAT5a/b are the most common pathways involved in prostate cancer cell survival and resistance." (PMID 36648960, 2023). "Co-incubation of mouse prostate cancer cells with T. vaginalis made adipocytes to increase production of IL-4, CCL2, and IL-6, as well as mRNA levels of CCL2, IL-4, and IL-13." (PMID 37125086, 2023). "The studies conducted so far, where the expression of IL-6 was confirmed in the immunohistochemical reaction, mainly concerned the differences between BPH and prostate cancer." (PMID 37847180, 2023). "Our results indicated that FFA C8:0 further regulates IL-6/p21 expression by regulating KLF7 and participates in the occurrence and development of prostate cancer." (PMID 37170248, 2023). "We demonstrated that ZQD regulated the IL6/STAT3 signaling pathway on the tumor microenvironment and thus inhibits the proliferation of prostate cancer cells." (PMID 37576403, 2023). "The increase in cell proliferation and chronic inflammation of the prostate activate the IL-6/STAT-3/cyclin D1 signaling pathway and play a significant role in the pathological progression of BPH and prostate cancer." (PMID 36601166, 2023). "In a similar method, which used a PDMS-based ECL-BPE array chip, multiple prostate cancer biomarkers including PSA, interleukin-6 (IL-6), and a prostate-specific membrane antigen (PSMA) were detected." (PMID 36140123, 2022). "The administration with 18α-GA can prevent the invasion of DU-145 prostate cancer cells by downregulating the levels of NF-ĸB (p65), VEGF and MMP-9, as well as HMGB1 and IL-6." (PMID 36313350, 2022). "In current work, we demonstrate that knockdown of Glut5 markedly blocked tumor cell proliferation in IL-6-expressed OSCC and prostate cancer xenografts." (PMID 35813468, 2022). "Further, the expression of Glut5 and IL-6 was found to be positively corelated in clinical samples of OSCC, prostate cancer, colorectal cancer and glioma, suggesting that the IL-6-medited Glut5 expression probably widely exist in multiple human cancers." (PMID 35813468, 2022). "The prostate cancer microenvironment has been reported to be characterized by a high secretion of regulatory molecules, such as TGF-β, IL-10, and IL-6." (PMID 35465350, 2022). "Here we show that treatment with IL-6 activates fructose uptake and fructolysis in oral squamous cell carcinoma (OSCC) cells and prostate cancer cells." (PMID 35813468, 2022). "We observed a higher secretion of IL-8, IL-6, M-CSF, and VEGF in DU145 prostate cancer cells when compared to 22Rv1 and LNCaP prostate cancer cells (∗∗∗p < 0.001)." (PMID 35465350, 2022). "Dual application of tocilizumab and stattic significantly repressed IL-6-induced expression of vimentin and VEGF and downregulation of E-cadherin in DU-145 prostate cancer." (PMID 36429126, 2022). "Another study also reported the absence of correlations between pretreatment and post-treatment serum concentrations of IL-4, IL-6, IL-10, and TNF-α, and fatigue symptoms in a group of 29 prostate cancer patients treated with radiotherapy." (PMID 36368974, 2022). "Prostate cancer is an inflammatory disease; however, we found that 4/11 (36.4%) inflammatory markers (IL-8, IL-1β, NSE, and IL-6 levels) were significantly lower in the PCa patients." (PMID 35664747, 2022). "In a recent study, Jiang et.al proved lycopene suppressed the inflammatory response by downregulating IL1, IL6, IL8, and TNF-α expression in prostate cancer." (PMID 34055003, 2021). "MALT1 facilitated NF-κB subunits (p50 and p65) nuclear translocation to induce gene expression of interleukin 6 (IL-6) and C-X-C motif chemokine 5 (CXCL5) in prostate carcinoma cells." (PMID 33802402, 2021). "The present study demonstrated that diosmetin is able to effectively alter the AKT and PKCα signaling cascade in prostate cancer cells, which can be activated by both IGF-1 and IL-6." (PMID 34682865, 2021).